CXCL10 (C-X-C motif chemokine ligand 10)
Diseases named in the same sentence as CXCL10 in open-access papers (continued):
Sharing a sentence is not in itself a finding about the gene and the disease.
pulmonary fibrosis (continued). "Studies have demonstrated an imbalance in the levels of angiogenic chemokines (ELR+ CXC chemokines [CXCL5 and CXCL8]) and angiostatic chemokines (interferon-inducible ELR- CXC chemokines [CXCL9, CXCL10, CXCL11]) in animal models of pulmonary fibrosis and lung tissue from patients with IPF." (PMID 39418259, 2024). "Serum concentrations of pro-inflammatory factors [IFN-γ, IL-1β, IL-12, IL-6, IL-8, IL-18, IP-10, MCP-1, CC-chemokine ligand-2 (CCL-2), and CXCL-10] are positively connected with pulmonary fibrosis and significant lung tissue destruction in SARS-coronavirus patients, according to the latest research." (PMID 37124230, 2023). "SARS-CoV-2 virus binds to angiotensin converting enzyme 2 (ACE2) and alters renin-angiotensin system activities, thus leading to enhanced inflammation (increased levels of VEGF, IP-10/CXCL10, MCP-3/CCL7, IL-6, IL-1, ROS etc.)and development of pulmonary fibrosis." (PMID 35139898, 2022). "Another effect of syndecan-4 may involve its interaction with the C-X-C motif chemokine ligand 10 (CXCL10), which shows an anti-fibrotic effect upon binding to syndecan-4 in a bleomycin-induced mouse model of pulmonary fibrosis." (PMID 28467516, 2017). "In the next step we analysed the TARC (CCL17)/IP-10 (CXCL10) ratio in our patient cohort as well as in cell culture, because a study by Kishi and colleagues revealed an elevated TARC (CCL17)/IP-10 (CXCL10) ratio in patients suffering from lung fibrosis." (PMID 26807786, 2016). "Transcriptomic data of people living with HTLV-1, HAM/TSP patients and idiopathic pulmonary fibrosis patients confirm in vivo expression of the in vitro gene signature, whereas single cell RNA-seq identified a unique myeloid subset in human lung, characterized by co-expression of CCL2/ISG15/CXCL10." (PMID 42026465, 2026). "Additionally, the levels of chemokines such as C-X-C motif chemokine ligand 10 (CXCL10) and chemokine (C-C motif) ligand 18 (CCL18) were elevated in the plasma and serum of post-COVID patients with pulmonary fibrosis, suggesting their involvement in chronic inflammation and fibrotic remodeling." (PMID 40872813, 2025). "The serum levels of CXCL9 and CXCL10 were higher in anti-Jo-1 antibody-positive DM-ILD patients than in those with idiopathic pulmonary fibrosis, which distinguished this disease entity from idiopathic pulmonary fibrosis and anti-signal recognition particle antibody-positive myositis." (PMID 34938325, 2021). "CXCL10 also did not decrease lung tissue-derived angiogenic activity and von Willebrand Factor expression after bleomycin delivery, despite that angiogenesis is considered a rate-limiting step in the development of pulmonary fibrosis." (PMID 33145014, 2020). "Interestingly, both CXCL9 and CXCL10 but not CXCL8, exert their effects via chemokine receptor CXCR3, and CXCR3-deficient mice are known to develop progressive interstitial pulmonary fibrosis." (PMID 27127180, 2016). "Here, we also demonstrate that CXCL10, CCL4, CXCL8 and IL-6-producing classical, non-classical monocytes and mDC profile identify a subset of patients characterized by the presence of lung fibrosis and decreased lung function." (PMID 29127442, 2018). "Current study also supports our hypothesis in a previous paper that a mutant CXCL10, without CXCR3-binding activity, delivered directly to the lungs could be a novel therapeutic agent in pulmonary fibrosis." (PMID 38771132, 2024).
dengue (60 papers, 2007 to 2026). "Among the chemokines analyzed, elevated levels of CXCL10/IP-10 in the dengue patients were associated with high levels of NS1 antigen." (PMID 34578370, 2021). "The upregulation of IL-6 and CXCL-10 expression had been reported previously as being associated with liver dysfunction in dengue patients." (PMID 34959637, 2021). "In Dengue patients, the severity of the disease has been associated with high plasma levels of IL-1RA and CXCL10." (PMID 31635238, 2019). "Our results show variation between IL-6 levels and increase in TNFα and CXCL10 serum levels to be associated with Dengue severity." (PMID 30112159, 2018). "We investigated the association of the cytokines TNFα, IL-6 and CXCL10 in patients with differing Dengue disease severity as compared with healthy controls." (PMID 30112159, 2018). "Using multiplex bead arrays and ELISAs, we observed that cytokines and chemokines associated with protection against dengue, namely CXCL10, IFN-α and TRAIL are produced by both monocyte subsets in response to dengue virus." (PMID 22574162, 2012). "Increased CXCL10 and TNFα are associated with increased disease severity in Dengue patients." (PMID 30112159, 2018). "If TNFα and CXCL10 were used as predictive biomarkers of disease progression, these biomarkers may aid in early identification of patients who are at a higher risk of more severe forms of Dengue." (PMID 30112159, 2018). "We measured and compared the levels of IL-18 and CXCL-10 with the different severity levels of Dengue." (PMID 41227147, 2025). "Neopterin in CSF had a cut-off value of 11.2 nmol/L, with 67% sensitivity and 63% specificity, while CXCL-10 in CSF showed a cut-off value of 156.5 pg/mL, with 91.7% sensitivity and specificity for neuroarbovirosis (dengue and neurochikungunya) diagnosis." (PMID 39861878, 2025). "CXCL10 (IP-10), a chemokine induced by interferon and a known marker of Dengue severity, was strikingly upregulated in infected monocytes." (PMID 41012666, 2025). "Next, we analyzed transcriptional changes in HLA-A, HLA-B, ISG15, and CXCL10 across Dengue disease severity." (PMID 41012666, 2025). "While several genes consistently identified dysregulated in dengue patients, such as CXCL10, ZWINT, BUB1, AURKA, STAT1, etc. there was a notable variability in gene expression patterns across the datasets." (PMID 40100920, 2025). "Further studies should explore the mechanistic role of IL-18 and CXCL10 in Dengue pathogenesis and their potential as therapeutic targets for managing severe cases of the disease." (PMID 41227147, 2025). "In contrast, interferon-stimulated genes (ISG15 and CXCL10) showed marked upregulation in Dengue patient monocytes, with the strongest expression observed in Dengue with warning sign." (PMID 41012666, 2025). "In a previous study of biomarkers in dengue and chikungunya neuroinvasive conditions, CXCL-10 in the CSF presented a 156.5 pg/mL cut-off with 91.7% sensitivity and specificity for the diagnosis of these conditions." (PMID 39205221, 2024). "For instance, in patients with dengue fever, the severity of the disease is connected with high levels of IL-1RA and CXCL10 in the plasma." (PMID 35154151, 2022). "The analysis of these inflammatory biomarkers, such as neopterin and CXCL-10, in the blood allows us to predict the severity of the course of dengue fever and chikungunya." (PMID 34959581, 2021). "The serological investigation of inflammatory markers CXCL-10 and neopterin provides support for the diagnosis and prognosis of dengue and chikungunya." (PMID 34959581, 2021). "In our study, higher plasma levels of the proinflammatory cytokines TNF-α, IL-6 and IL-18, and the anti-inflammatory cytokine IL-10 and the chemokines CXCL8/IL-8, CCL2/MCP-1 and CXCL10/IP-10 were found in the dengue patients compared to the healthy controls." (PMID 34578370, 2021).
dengue (continued). "CXCL-10/IP-10 is an important pro-inflammatory marker in the case of dengue and chikungunya, where there is an increase in this chemokine when induced by IFN-γ, mainly associated with more severe cases and in pregnant women." (PMID 34959581, 2021). "We investigated the association of circulating levels of cytokines such as Interleukin (IL)-6, tumor necrosis factor (TNF)-alpha and CXCL-10 in Dengue patients with differing severity of disease." (PMID 30112159, 2018). "CXCL10 secretion levels were increased in each of the Dengue groups; DF (P <0.001), DWS (P <0.001) and SD (P <0.001) as compared with healthy controls." (PMID 30112159, 2018). "We observed that TNFα and CXCL10 levels were raised in patients with Dengue as compared with healthy controls." (PMID 30112159, 2018). "Circulating levels of TNFα (p≤0.001) and CXCL10 (p≤0.001) levels were increased in Dengue patients as compared with controls." (PMID 30112159, 2018). "When comparison was made between Dengue groups, CXCL10 levels were also found to be raised in DWS as compared with DF (P=0.046)." (PMID 30112159, 2018). "Particularly, we observed that circulating levels of TNFα and CXCL10 differed between Dengue patients with severe as compared with mild disease." (PMID 30112159, 2018). "Patients with Dengue had raised levels of CXCL10 (P <0.001) and TNFα (P <0.001) as compared with healthy controls." (PMID 30112159, 2018). "CXCL10 is a well-known mediator of inflammatory responses where its gene has been upregulated in PBMCs of dengue patients." (PMID 24647042, 2014). "Median levels of Angptl3, IL-18BP, CXCL10, Platelet Factor 4, sICAM-1, Factor D, sEng and sKDR were higher in dengue fever compared to leptospirosis (p < 0.001 for all)." (PMID 24444080, 2014). "We also show that monocyte subsets were equally capable of producing anti-viral factors associated with dengue protection, such as IFN-α, CXCL10 and TRAIL." (PMID 22574162, 2012). "Furthermore, based on the analysis of ROC curves, we determined the cut-off values of IL-18 and CXCL-10 for predicting Dengue severity." (PMID 41227147, 2025). "In addition, we revealed a positive correlation of CXCL-10 with liver enzymes in all patients with Dengue." (PMID 41227147, 2025). "IL-10 and CXCL10 were previously shown to be markers of dengue severity and plasma leakage." (PMID 36595532, 2023). "In contrast, during convalescent DENV infection, the mean levels of IFN-γ, CXCL10, IL-4, and IL-10 remained relatively high, suggesting that the sustained interplay of Th1, Th2, and Treg may be needed for dengue control in this setting." (PMID 37235332, 2023). "The detection of severe cases of dengue fever found that the expression of pro-inflammatory cytokines (IL-1, TNFα), anti-inflammatory cytokines IL-10 and chemokines (IL-8, CXCL10) were significantly up-regulated, and this cytokine storm was associated with plasma leakage and hemorrhage." (PMID 35154151, 2022). "Moreover, severe cases of Dengue with increased levels of pro-inflammatory cytokines such as IL-1 and TNFα, anti-inflammatory cytokine IL-10 and chemokines including IL-8 and CXCL10 have been reported." (PMID 31635238, 2019). "Increased CXCL10 and TNFα levels in patients with Dengue as compared with healthy controls." (PMID 30112159, 2018). "We determined CXCL10, IL-6 and TNFα levels in Dengue patients categorized into DF, DWS and SD." (PMID 30112159, 2018). "Nine biomarkers differed significantly between dengue fever and leptospirosis, with higher levels of Angptl3, IL-18BP, IP-10/CXCL10, Platelet Factor 4, sICAM-1, Factor D, sEng and sKDR in dengue and higher levels of sTie-2 in leptospirosis (p < 0.001 for all comparisons)." (PMID 24444080, 2014). "However, like HMC-1 cells, KU812 cells did produce CCL4, CCL5 and CXCL10 in response to antibody-enhanced dengue virus infection." (PMID 22479521, 2012).
dengue (continued). "Patients with dengue hemorrhagic fever (DHF) had significantly higher NS1,CXCL-8, and CXCL-10 serum levels thanthose with classic dengue fever (DF)." (PMID 39082520, 2024). "In addition, weinvestigated the CXCL-10 production after in vitroIFN-γ stimulation of PBMCs from 48 DV-infected individuals(with different clinical forms of dengue fever) and 20 NI individuals usingELISA, and CD119 expression on CD14+ cells with flow cytometry." (PMID 39082520, 2024). "Among them, a vast panel of increased cytokines and chemokines in severe dengue, such as IFN-γ, GM-CSF, IL-10, CCL4/MIP-1β, IL-1β, CXCL8/IL-8 TNF-α, CXCL10/IP-10, CCL2/MCP-1, and IL-18." (PMID 35631030, 2022). "We used the KU812 cell line to demonstrate for the first time that anti-dengue antibodies enhanced infectious Zika virus replication in a mast cell model and specifically increased CCL5, CXCL10, and IL-1β, while also impairing granzyme B secretion." (PMID 35862953, 2022). "CXCL10 neutralization has been effective in attenuating NK and CD8 T cell-mediated hepatocellular injury during fulminant Dengue virus infection." (PMID 24890566, 2014). "It was found that for CBMCs, polyI:C and antibody-enhanced dengue virus infection were able to induce significant levels of CCL4, CCL5 and CXCL10." (PMID 22479521, 2012). "PCR quantification of the same transcripts in patients with acute versus convalescent dengue disease showed highly elevated fold changes for CCL2, -8 and CXCL10 but a more modest enrichment of MIP-1α at fold change 3.5." (PMID 21810247, 2011). "Moreover, serum levels of IL-15, CCL-2, CXCL-10, and CXCL-11 correlated with dengue severity in humans." (PMID 40934228, 2025). "In addition, our study found a positive association between APRI values and the levels of pro-inflammatory cytokines, chemokines and coagulation mediators (IL-6, IL-18, CXCL10/IP-10 and TFPI) in dengue patients." (PMID 34578370, 2021). "Increased levels of TNF-α, IL-1β, IL-4, IL-6, IL-8, IL-13, IL-15, macrophage migration inhibitory factor (MIF), and chemokines CCL2, CCL4, CCL5, and CXCL10 (IP-10) among others, have been reported in patients with dengue hemorrhagic fever (DHF) when compared to dengue fever (DF)." (PMID 29986388, 2018). "There were five biomarkers where the median levels were outside the population-derived normal range in dengue fever, but not leptospirosis: Angptl3, IL-18BP, CXCL10, sICAM-1, and sEng." (PMID 24444080, 2014). "While monocyte-derived dendritic cells can produce large amounts of CCL4 and CXCL10 in response to dengue virus, they are not resident in the dermis as mast cells are, and would not be activated immediately upon dengue virus infection." (PMID 22479521, 2012). "Mast cells responded to antibody-enhanced dengue virus infection or polyinosiniċpolycytidylic acid treatment with the production of type I interferons and the rapid and potent production of chemokines including CCL4, CCL5 and CXCL10." (PMID 22479521, 2012). "Comparing whole genome expression profiles between patients with acute versus convalescent dengue disease indicated significant abundance of transcripts of the chemokines CCL2 (4,287 fold), CCL8 (160 fold), CXCL10 (30 fold) and CCL3 (17 fold) during acute dengue." (PMID 21810247, 2011). "The response of PBMCs toIFN-γ stimulation was lower in patients with DHF thanin those with DF or dengue with complications (DWC), with lower CD119expression and reduced CXCL-10 synthesis." (PMID 39082520, 2024). "As in our previous studies, the dengue patients had high plasma levels of the cytokines TNF-α (p < 0.001), IL-6 (p = 0.005), IL-10 (p < 0.001) and, IL-18 (p = 0.001) and the chemokines CXCL8/IL-8 (p < 0.001), CCL2/MCP-1 (p < 0.001), CXCL10/IP-10 (p = 0.001) compared to healthy controls." (PMID 34578370, 2021).
dengue (continued). "Blood samples of patients with Dengue were only collected at a time point of admission for measuring of IL-18 and CXCL-10; therefore, we did not monitor dynamic changes in IL-18 and CXCL-10 levels during the course of the disease." (PMID 41227147, 2025). "Further ROC analysis revealed that the cut-off values for distinguishing severe Dengue from non-severe Dengue for IL-18 and CXCL-10 were both 669.65 pg/mL, whereas that of CXCL-10 was 3739.5 pg/mL." (PMID 41227147, 2025). "Although all three ligands are induced by dengue virus infection, CXCL9 and CXCL11 could not compensate for the absence of CXCL10 in Cxcl10-/-mice." (PMID 24939012, 2014).
systemic lupus erythematosus (60 papers, 2008 to 2025). An autoimmune multi-organ disease typically associated with vasculopathy and autoantibody production. "Meanwhile, CXCL10 was associated with UC progression, and it was up-regulated in cytokine activity, complement and coagulation cascades, cytokine-cytokine receptor interaction, and systemic lupus erythematosus, which shed light on the drug target for UC patients." (PMID 34592880, 2021). "Previous studies have shown that Fli-1 is a positive regulator of CCL2, CCL3, CCL4, CCL5, CXCL9, and CXCL10 in the kidneys of Fli-1 heterozygote knockout mice with lupus and CXCL5 in dermal small vessels from Fli-1 knockout mice." (PMID 40305194, 2025). "Reduced Fli-1 expression in lupus mice leads to decreased renal Cxcl10 mRNA levels and renal infiltrating CXCR3+ T cells that parallels reduced renal inflammatory cell infiltration and renal damage." (PMID 37790939, 2023). "We found that expression of CCL2, CCL3, CCL4, CCL5, CCL8, CCL19, and CXCL10 increased 1.6–5.6-fold in the kidney of lupus-prone MRL.Faslpr mice with advancing age from 9 to 16 weeks." (PMID 37567910, 2023). "The CXCL10/CXCR3 axis plays a role in the pathogenesis of various inflammatory diseases including lupus." (PMID 37790939, 2023). "We also found that expression of CCL2, CCL3, CCL4, CCL5, CCL8, CCL19, and CXCL10 increased 1.6–5.6-fold in the kidney of lupus-prone MRL.Faslpr mice with advancing age from 9 to 16 weeks." (PMID 37567910, 2023). "Our present study reports for the first time that FLI-1 impacts CXCL10 protein expression in kidneys of lupus mice and inflammatory cells." (PMID 37790939, 2023). "We showed that globally reducing FLI-1 levels in a lupus prone mouse strain reduced renal Cxcl9 and Cxcl10 gene expression and renal-infiltrating CXCR3+ T cells, and that FLI-1 can upregulate Cxcr3 promoter activity in T cells." (PMID 37790939, 2023). "The RhoA/ROCK inhibitor in turn reduced type I IFN-induced STAT-1 phosphorylation and ISRE reporter gene expression, as well as OAS1 and CXCL10 in human lupus PBMCs." (PMID 37790522, 2023). "CXCL10, also known as interferon-gamma-inducible protein 10 (IP-10), has shown its value in lupus patients." (PMID 33670423, 2021). "We also found that deleting IL-22 or IL-22R downregulated CCL2 and CXCL10 expression, and decreased the filtration of macrophage into the kidney of lupus-prone mice." (PMID 33717066, 2021). "CXCL10 has been shown to be increased in mouse models and lupus patients and is an important biomarker of lupus." (PMID 33042154, 2020). "At the human disease level, serum levels of interferon-controlled chemokines (e.g. CCL19 and CXCL10) have been found to correlate with current lupus activity, disease flare-up, and disease remission." (PMID 26981635, 2016). "CCL2, CCL3, CCL5, CXCL10, and CXCL16 are increased in lupus nephritis patients and lupus-prone MRL.Faslpr mice." (PMID 37567910, 2023). "The aim of this study was to investigate the correlation between IFN-α-induced chemokines CCL2, CXCL10 and CCL19 and disease activity in patients with systemic lupus erythematosus." (PMID 35207538, 2022). "Upregulation of Axl, Clec7a, Itgax, Ccl5, and Cxcl10 was also observed in NZB/NZW mice, indicating common lupus pathology." (PMID 31888754, 2019). "Among the secreted pro-inflammatory cytokines/chemokines analyzed (IL-6, IL12p70, and CXCL10), the strongest suppressive effect was on CXCL10, a highly Type I IFN-dependent cytokine, upon CpG stimulation, both in normal and lupus-prone DCs." (PMID 29456540, 2018). "Two different combined inflammatory and lymphoid chemokine scores were investigated using CCL2, CXCL10 and CCL19 (score used successfully in lupus) and CXCL9, CXCL10, CXCL13 and CCL19 data." (PMID 24278364, 2013). "In this regard, it has been reported that levels of CXCL9, CXCL10 and CXCL11 correlate with lupus disease activity." (PMID 21050432, 2010).